OR12D1 (olfactory receptor family 12 subfamily D member 1 (gene/pseudogene))
Description:
Odorant receptor.
Synonyms: hs6M1-19; formerly OR12D1P
Gene: Protein-coding gene on chromosome 6 (29,414,928 to 29,418,905, forward strand). Ensembl gene ENSG00000251608.
Subcellular location: Cell membrane
Homologues: Paralogues in human: OR12D2 (62% identical), OR12D3 (50% identical), OR7A17 (37% identical), OR1L1 (37% identical), OR7A5 (37% identical), OR1L3 (36% identical), OR1L6 (36% identical), OR1L4 (36% identical), OR4C45 (36% identical), OR7A10 (36% identical), OR1G1 (35% identical), OR4N2 (35% identical), and 116 more.